PPARGC1A (PPARG coactivator 1 alpha)
Diseases named in the same sentence as PPARGC1A in open-access papers (continued):
Sharing a sentence is not in itself a finding about the gene and the disease.
metabolic disease (136 papers, 2007 to 2026). A congenital disorder (due to inherited enzyme abnormality) or acquired (due to failure of a metabolically important organ) disorder resulting from an abnormal metabolic process. "The rs8192678 polymorphism of the PPARGC1A gene, beyond its role in sports performance, has a significant impact on metabolism regulation, and its association with various metabolic diseases has been extensively studied." (PMID 39766897, 2024). "Here, we report that p16Ink4a-Cdk4-E2F3 signals regulate muscle metabolic function via targeting the mitochondrial biosensor PPARγ coactivator 1-α (PPARGC1A, which encodes to PGC-1α) that is also linked to muscle fiber–type specification and metabolic disease." (PMID 37395281, 2023). "Although the effects of PPARGC1A SNPs are only reported in these three populations, the polymorphisms of PPARGC1A have been linked to many other metabolic diseases, thus highlighting its possible contribution to NAFLD disease." (PMID 36672614, 2022). "Additionally, the interaction between FGF21 and PPARGC1A pathways is crucial for understanding metabolic disorders." (PMID 41465464, 2025). "Additionally, the influence of circulating microRNAs and the upregulation of PPARGC1A offer promising avenues for further understanding and therapeutic intervention in metabolic disorders." (PMID 41465464, 2025). "Importantly, interactions between SIRT1, peroxisome proliferator-activated receptor gamma coactivator 1 (PPARGC1A), and FOXO1/FOXO3 indicate a strong mitochondrial and antioxidant component, aligning with their roles in metabolic disease and aging." (PMID 40664894, 2025). "PPARA, PPARGC1A, and PPARGC1B, which are involved in the fatty acid oxidation of PLN-KO hiPSC-CMs, began to decline at day 30, while genes involved in glucose utilization, such as GNPNAT1, PGM3, and GFPT1, were upregulated, indicating that energy metabolism disorders began to occur." (PMID 35334215, 2022). "Notably, PPARG and PPARGC1A were central activated upstream regulators in VAT vs. SAT of NK cows, thus implying that, like in humans, PPARG agonism might be a potential therapeutic target for metabolic disorders in dairy cows." (PMID 40599780, 2025).
neurodegenerative disease (82 papers, 2009 to 2025). A disorder of the central nervous system characterized by gradual and progressive loss of neural tissue and neurologic function. "It was then not surprising that IPA outputs revealed upstream regulators and master regulators that too have been strongly implicated in neurodegenerative disease such as PPARG coactivator 1 alpha (PPARGC1A) and the mitochondrial uncoupling protein Thermogenin (UCP1)." (PMID 35093178, 2022). "The regulation of these isoforms may be relevant, as experimental and genetic studies implicated the PPARGC1A locus in neurodegenerative diseases." (PMID 31471878, 2020). "Comparatively, our findings are consistent with existing literature indicating the crucial roles of AKT1 and PPARGC1A in neurodegenerative diseases." (PMID 40642087, 2025). "The transcriptional regulator peroxisome proliferator activated receptor gamma coactivator 1A (PGC-1α), encoded by PPARGC1A, has been linked to neurodegenerative diseases." (PMID 33804860, 2021). "YY1 is a ubiquitous transcription factor previously noted to regulate several genes associated with neurodegenerative diseases including BACE1 and APP, SNCA, EAAT2, MTOR and PPARGC1A." (PMID 25187168, 2014). "The metabolic master regulator PGC-1α, coded by the PPARGC1A gene, coordinates cellular respiration and was shown to play a role in neurodegenerative diseases, including HD." (PMID 24383721, 2014). "For instance, in the context of neurodegenerative diseases, mitochondrial dysfunction has been linked to increased susceptibility to apoptosis, regardless of the expression of genes like PPARGC1A." (PMID 41614832, 2025). "Thus, CNS-specific isoforms markedly amplify the biological functions of PPARGC1A and CNS-specific isoforms and reference proteins have common, complementary and selective functions relevant for neurodegenerative diseases." (PMID 33804860, 2021).
infection (49 papers, 2007 to 2026). The state of being infected such as from the introduction of a foreign agent such as serum, vaccine, antigenic substance or organism. "Analysis of our deposited dataset in Gene Expression Omnibus (GEO) (GSE11348) indicated downregulation of PPARGC1A at 48 h post-HRV-16 infection." (PMID 34135327, 2021). "In our initial evaluation of the effect of HRV-C15 infection on six metabolic-associated genes, we found that levels of HK2 (HK2) and PPARGC1A (PGC-1α) were most altered during HRV-C15 infection." (PMID 34135327, 2021). "In contrast, genes associated with ECM organization (Col4a5, Col4a6, Col6a4), microtubule polymerization formation (Tppp, Tppp3), and mitochondrial biogenesis (Ppargc1a) were found to be among the top down-regulated DEGs during infection." (PMID 29339782, 2018). "The increase of Ppargc1a transcripts was also observed in splenic macrophages recovered from mice at 48 hours post-infection." (PMID 25738568, 2015). "We found an early up-regulation of Ppargc1a and Ppargc1b post-infection (at 6 h) in WT mice, but the expression of both genes was concordantly dysregulated in TLR2−/− mice (no increase at 6 h) and in TLR4−/− mice (amplified at 6 h)." (PMID 20657826, 2010). "While oligomycin A sustained PPARGC1A transcription at 24 h post infection, ZLN005 was unable to sustain high transcription levels, which may explain its less efficacious barrier recovery potential." (PMID 34135327, 2021). "RNAseq analysis indicated that PPARGC1A is also downregulated in patients during HRV-39 infection." (PMID 34135327, 2021). "In both clinical studies, HRV-16 and HRV-39 considerably downregulated PPARGC1A during infection." (PMID 34135327, 2021). "Finally, the observation that sustaining increased expression of PPARGC1A beginning at 2 h post infection using ZLN005 or oligomycin A abrogated the marked disruption of epithelial architecture normally induced by HRV-C15 at 24 h post infection." (PMID 34135327, 2021). "During the late phase of infection, there was a rebound in VDAC expression, induction of BAK1 (+1.16 at 48 h), and a significant reduction in PPARGC1A at 72 h (−1.63), which reduced mitochondrial resiliency." (PMID 41568347, 2025). "PCR analysis revealed ZLN005 treatment resulted in a significant increase in PGC-1α mRNA (ppargc1a) compared to control, and attenuated MAC-mediated decreases during 6-hour infection and 24-hour infection." (PMID 39913377, 2025). "While PPARGC1A mRNA expression was attenuated by SR18292, HRV-C15 titers remained unchanged at 12 h post infection." (PMID 34135327, 2021). "To further confirm HRV downregulation of PPARGC1A by other clinically approved HRV strains, we used data from an ongoing experimental infection study infecting healthy volunteers with GMP grade HRV-39." (PMID 34135327, 2021). "Because HRV-C15 downregulates PGC-1α by 8–12 h post infection, we investigated the effect of oligomycin A on the expression of either HK2 or PPARGC1A and observed that it markedly increases PPARGC1A expression." (PMID 34135327, 2021).
cardiovascular diseases (34 papers, 2008 to 2025). "Recently, other PPARGC1A polymorphisms were shown to be associated with presence of self-reported cardiovascular disease, and it was suggested that this association was mediated via DNA damage." (PMID 19077249, 2008). "Impaired activity of PPARGC1A has been linked to elevated oxidative stress and inflammation, which may underlie the development of various metabolic and cardiovascular diseases." (PMID 40423083, 2025). "Polymorphic loci of four genes whose products are involved in blood pressure control (ACE, BDKRB2, NOS3 and PPARGC1A) can be used in martial arts not only to determine predisposition to cardiovascular disease but also to predispose to the development of speed and power qualities and endurance." (PMID 36140844, 2022). "The complexity of the role of PPARGC1A in cardiovascular disease certainly warrants further research and the clinical importance of the present findings has to be established in further studies." (PMID 19077249, 2008). "Our research is considered a preclinical application for the treatment of potential cardiovascular diseases through the browning of epicardial adipose tissue (EAT), based on the activation of BAT-specific genes such as UCP1, PRDM16, and PPARGC1A (PGC-1α) in human EAT." (PMID 33271769, 2020).
kidney disease (34 papers, 2013 to 2025). "Among them were several genes known to be involved in kidney diseases, such as Kdm5a, Rb1, Tead1, Xbp1 and Ppargc1α with so far unknown role as sexual dimorphism regulators." (PMID 39278930, 2024). "Our findings of inverse associations of rs7672915, intron 2 in subgroups (older age, with renal impairment, and antiplatelet users) could be random findings or due to the role of PPARGC1A in mitochondria subsequently affecting the aging process, kidney disease, and platelet function." (PMID 35812313, 2022). "Studies on gene-environment interactions have suggested significant genetic and environmental factors such as smoking, waist circumference, and sex for eNOS rs2070744, PPARGC1A rs8192678, KCNQ1 rs2237895, and KCNQ1 rs2283228 with kidney disease." (PMID 37187702, 2023).
myopathy (15 papers, 2012 to 2022). A disease of the muscle in which the muscle fibers do not function properly. "Still, two out of four fibroblast lines from myopathy patients showed a high expression of the nuclear-encoded PPARGC1A gene, as compared to the highest expression found in the five control fibroblast lines." (PMID 35216315, 2022). "Most notably, the PPARGC1A expression showed a positive correlation with the mitochondrial copy number when taking both the control and myopathy fibroblasts into consideration (r= 0.85; p < 0.005)." (PMID 35216315, 2022). "Next, we compared the expression of selected mtDNA-encoded genes (CYTB, COX1, ND1, and ND6) and nuclear-encoded genes involved in mitochondrial biogenesis (PPARGC1A and transcription factor A (TFAM)) in skin fibroblasts from healthy controls versus those from myopathy patients." (PMID 35216315, 2022).
kidney (13 papers, 2014 to 2023). "In addition to anatomic site, other factors may affect the interaction between diet-associated inflammation and a PPARGC1A genetic variant in colorectal carcinogenesis." (PMID 28051997, 2017). "Transgenic expression of Ppargc1a and Ppara showed protection from acute kidney injury and kidney fibrosis and also rescued the phenotype of the tubule-specific Notch transgenic mice, indicating the key role of metabolic pathways in kidney function and tubule health." (PMID 30226866, 2018).
mitochondrial disease (13 papers, 2013 to 2022). "Several studies have focussed on peroxisome proliferator-activated receptor (PPAR) gamma co-activator 1 alpha (PGC-1α, encoded by PPARGC1A) as a potential treatment for mitochondrial disease." (PMID 27190030, 2016).
PPARGC1A also shares sentences with these, for which no sentence is quoted: Cognitive impairment (47 papers); neuroblastoma (37); acute kidney injury (35); amyotrophic lateral sclerosis (29); myocardial ischemia (25); Stroke (24); Cerebral ischemia (23); Cachexia (22); ischemic stroke (21); endothelial dysfunction (20); neurological diseases (19); nonalcoholic fatty liver disease (19); ischemic heart disease (17); renal cell carcinoma (16); Atrophy (15); glioblastoma (14); hyperlipidemia (13); lipid metabolism disorders (13); brain injury (12); heart disease (12); muscle atrophy (12); muscular dystrophy (12); breast tumors (11); Duchenne muscular dystrophy (11); glioma (11); nasopharyngeal carcinoma (11); renal carcinoma (11); cholangiocarcinoma (10); congestive heart failure (10); endometrial cancer (10).
A further 362 diseases each share a sentence with PPARGC1A in 10 papers or fewer.